KCNJ5-AS1 (KCNJ5 antisense RNA 1)
Synonyms: C11orf45; MGC35558; FLJ43646
Gene: Long non-coding RNA gene on chromosome 11 (128,875,874 to 128,906,044, reverse strand). Ensembl gene ENSG00000174370.
Subcellular location: Secreted
Genetic constraint (gnomAD): Loss-of-function variants: 6 observed, 8.54 expected, observed/expected ratio (o/e) 0.7, 90% interval 0.38 to 1.38. That is too few expected variants to judge how well the gene tolerates losing a copy. Missense variants: 126 observed, 153.92 expected, observed/expected ratio (o/e) 0.82, 90% interval 0.71 to 0.95. Synonymous variants: 55 observed, 59.72 expected, observed/expected ratio (o/e) 0.92, 90% interval 0.74 to 1.15.
Diseases named in the same sentence as KCNJ5-AS1 in open-access papers:
KCNJ5-AS1 is named in the same sentence as 4 diseases in open-access papers, as found by Europe PMC text mining. Sharing a sentence is not in itself a finding about the gene and the disease.
KCNJ5-AS1 shares sentences with these, for which no sentence is quoted: breast carcinoma (1 paper); cancer (1); Tourette syndrome (1); tumor (1).